APP (amyloid beta precursor protein)
Diseases named in the same sentence as APP in open-access papers (continued):
Sharing a sentence is not in itself a finding about the gene and the disease.
memory impairment (continued). "In transgenic APP/PS1 mice, NAC administration prevents passive avoidance memory impairment, suppresses brain protein oxidation and S-nitrosylation, decreases Aβ-40 and Aβ-42 hippocampal levels and restores contextual fear memory and hippocampal LTP." (PMID 30574085, 2018). "Our results showed that although persistent and robust monoarthritis pain was induced by the FCA injections, only the transgenic APP/PS1 mice with chronic monoarthritis pain exhibited marked learning and memory impairments." (PMID 28553223, 2017). "Memory improvement upon Nrf2 level modulation has been reported in aged APP/PS1 mice and in rats with induced memory impairments." (PMID 26635523, 2015). "This was the case for a wide range of molecular (APP expression and processing; gene expression), electrophysiological (EEG), and neurobehavioral (motor impairments; learning and memory impairments) features of the model." (PMID 25883808, 2015). "The present study was conducted in order to investigate the effect of varying caffeine doses on memory impairment and the expression of brain BNDF and TrkB in PS1/APP double transgenic mice." (PMID 23900282, 2013). "New evidence points to β-derived metabolites of APP, especially ß-CTF, as the synaptic-toxic APP fragments mediating synaptic and memory impairments." (PMID 23451158, 2013). "On the other hand, APP-HFD mice show more significant memory impairment than WT-HFD mice, suggesting that the memory impairment in APP-HFD mice was attributable to an interaction between HFD and APP metabolism." (PMID 24023774, 2013). "The objective of this study was to investigate the effects of varying doses of caffeine on memory impairment and the expression of brain neurotrophic derived factor (BNDF) and TrkB in PS1/APP double transgenic mouse models." (PMID 23900282, 2013). "In our preliminary experiments, we found that 9-month-old APP/PS1 mice did not exhibit memory impairment in the new object recognition and social cognitive memory tests." (PMID 40792034, 2025). "Other studies also demonstrated that NBP treatment attenuated depression‐like behaviors and ameliorated spatial learning and memory impairment by upregulating the expression of p‐ERK and p‐Akt in rats exposed to chronic suspension stress and APP/PS1 transgenic AD mice." (PMID 36756709, 2023). "Despite these alterations, no memory impairment was observed in APP/PS1 mice in the novel object recognition test." (PMID 37090809, 2023). "APP/PS1 mice develop amyloid plaques and show memory impairment." (PMID 36909366, 2023). "At a young age, high levels of APP can reduce developmental spine pruning and impair synaptic long-term depression (LTD) with changes in synaptic development and plasticity, resulting in ASD and memory impairment." (PMID 37762342, 2023). "The findings demonstrated that the APP/PS1 mice exhibited prolonged escape latency and fewer crossings in the platform quadrant compared with the WT mice, suggesting the presence of learning and memory impairments akin to those seen in AD." (PMID 37629027, 2023). "Besides, the percentage of correct alternation arm was significantly decreased in the diabetic and APP/PS1 mice when compared with the controls (P <0.05), signifying that diabetic and 8-month-old APP/PS1 mice had already developed memory impairment." (PMID 35996379, 2022). "However, in APP/PS1 mice treated with BG45 for 12 days, learning and memory impairments were obviously improved." (PMID 36558932, 2022). "In the spatial probe test, compared to the control group, we observed that the times of crossing platform as well as the time staying on the platform were decreased in APP/PS1 transgenic mice compared with the control group, which showed visible memory impairment." (PMID 33478552, 2021). "Together, these data suggest that clemastine treatment can rescue the short-term memory impairment but not the memory retention deficits or learning ability impairment of the aged APP/PS1 mice." (PMID 34746130, 2021).
memory impairment (continued). "To test this hypothesis, in this study, we took advantage of the availability of mouse models of AD (APP/PS1), which display memory impairment, and AD human samples to address the role of pro-NGF/p75NTR signaling in different aspects of adult neurogenesis." (PMID 34639085, 2021). "Unlike APP mice, PS transgenic do not display memory impairments, nor prominent amyloid plaque per se." (PMID 34520451, 2021). "APP/PS1 mice are known to develop AD‐like pathology and memory impairments." (PMID 31877583, 2020). "Remarkably, APP/PS1 mice that had received such treatment showed no learning or memory impairment at 23–25 weeks of age, i.e., 8 weeks after the end of the treatment." (PMID 31431685, 2020). "Neuropathological hallmarks of AD include the deposition of Amyloid-β (Aβ) plaques derived from Amyloid Precursor Protein (APP) and neurofibrillary tangles (NFT) made up of the Tau protein, leading to progressive cognitive and memory impairment accompanied by alteration in behaviour and personality." (PMID 31963395, 2020). "Meanwhile, the altered synaptic proteins PSD95 and synaptotagmin in the APP/PS1 mice were significantly recovered, suggesting that CPPs might alleviate AD related memory impairment by restoring synapse related proteins and thus synaptic plasticity." (PMID 32652518, 2020). "Importantly, the overexpression of TrkB-FL in the AD APP/PS1 mouse model, reduces memory impairment." (PMID 30774582, 2019). "Furthermore, transgenic mice expressing the C-terminal intracellular domain of APP (AICD) developed Alzheimer's-like symptoms, such as accumulation of phosphorylated tau and memory impairment." (PMID 29440986, 2018). "When we performed a probe test 24 h after the last training trial, the Fe-treated APP/PS1 mice showed no preference toward the target quadrant, indicating significant memory impairment, whereas the M-30 or NS398-treated APP/PS1 mice performed as well as the WT C57BL/6 mice." (PMID 30383537, 2018). "In this study, APP/PS1 transgenic mice were utilized to examine whether chronic treatment of ICS II could improve spatial learning and ameliorate memory impairments." (PMID 28337142, 2017). "In contrast, treatment using the classical formula HLJDT did not reduce the memory impairment of 3XTg-AD mice and, rather, increased the Aβ/Fl-APP/CTFs in both animal and cell culture studies." (PMID 28740171, 2017). "Our findings do suggest that a reduction in SWDs is not sufficient to reverse memory impairments in APP/PS1 mice, but future studies using a different experimental design are required to extend the generalizability of this finding." (PMID 25945128, 2015). "Thus, although both brivaracetam and ethosuximide significantly reduced SWDs in APP/PS1 mice, only brivaracetam reversed memory impairments in this model." (PMID 25945128, 2015). "These type 2 DM models show increased levels of Aβ and the β-secretase-cleaved C-terminal fragment of APP (β-CTF or C99, an intermediate β-metabolite of APP) concomitant with BACE1 elevations in the hippocampus and cerebral cortex, leading to learning and memory impairments." (PMID 41446639, 2025). "Nonetheless, research using 2-month-old APP/PS1 mice supplemented with full sugar chocolate pudding across an 8-week time course demonstrated globally increased cerebral amyloid-beta plaques and demonstrated memory impairments in the novel object recognition test." (PMID 39452073, 2024). "Consequently, we cannot rule out the possibility that the memory impairments seen in J20 mice are due to human APP overexpression." (PMID 36517890, 2022). "Especially, FGF2 treatment inhibited Aβ production in primary cultured neurons of APP/PS1 mice and APPswe-HEK293 cells and improved synaptic transduction, plasticity, and neurogenesis in an APP/PS1 mouse, while reducing hippocampal Aβ deposition and memory impairment." (PMID 34071457, 2021).
memory impairment (continued). "The probe test confirmed that hM4Di-expressing APP/PS1-PV-Cre mice had also no memory impairments as they spent significantly more time in the target quadrant, similar to WT-PV-Cre mice, whereas mCherry-expressing APP/PS1-PV-Cre mice showed a clear memory deficit and performed at chance level." (PMID 31431685, 2020). "Thus, PV hyperexcitability in APP/PS1 mice coincides with spatial learning and memory impairments." (PMID 31431685, 2020). "Furthermore,APP/E4 mice, but not APP/E2 mice, exhibit memory impairment on objectrecognition and radial arm maze tests." (PMID 24972680, 2014). "In addition to anti-parkinsonian potential, KDS2010 effectively ameliorated memory impairment in the APP/PS1 transgenic mouse model of AD regardless of whether treatment was short-term (3 days) or long-term (30 days)." (PMID 34611843, 2021). "Moreover, memory impairment has been demonstrated in APP transgenic mice even without Aβ deposition, suggesting that other non-AD-related confounding factors might play a role." (PMID 32914393, 2021). "Thus, tau depletion failed to reverse the memory impairment induced by over-production of APP." (PMID 29545742, 2018). "In addition, APP-SL 7-5 Tg mice were administered nobiletin daily from 4 to 9 months of age, and it significantly reversed memory impairment without affecting general behavior in the context-dependent fear conditioning test and reduced quantity of Aβ1-42 and Aβ1-40 in the brain." (PMID 28869548, 2017). "Despite the widespread use of APP/PS1 mice, memory impairment is not reported consistently across behavioral paradigms." (PMID 37250187, 2023). "In the probe trial both lesioned and sham-lesioned APP/PS1 mice had similar poor performance, likely reflecting memory impairment due to the animals’ age and genotype, irrespective of lesion status." (PMID 36323689, 2022). "The 6-month-old APP/PS1 transgenic mouse model showed significant spatial learning and memory impairment, but there was no significant recognition memory impairment." (PMID 32595486, 2020). "APP and APP/PS1 transgenic mice develop age-dependent amyloid deposits and memory impairments in the absence of tau inclusions." (PMID 26379494, 2015). "In fact, APP/PSEN1-Tg animals could not discriminate between familial and novel object 2, indicating important memory impairments." (PMID 33795014, 2021). "However, CB2 receptor ablation does not affect the survival of APP/PSEN1 mice and has no impact on memory impairment or TAU hyperphosphorylation." (PMID 34001284, 2021). "When we performed a probe test at 24 h after the last training trial, the untreated APP/PS1 Tg mice showed no preference for the target quadrant, which indicated significant memory impairment, whereas the BDNF-treated APP/PS1 Tg mice performed better than the non-treated APP/PS1 Tg mice." (PMID 28377712, 2017).
familial Alzheimer disease (170 papers, 2006 to 2026). A degenerative disease of the brain that causes gradual loss of memory, judgment, and the ability to function socially. "Today, 13 intra-amyloid-β (Aβ) amyloid precursor protein (APP) gene mutations are known to cause familial Alzheimer’s disease (AD)." (PMID 41044681, 2025). "Variants in the APP gene are associated with both familial Alzheimer’s disease and cerebral amyloid angiopathy." (PMID 41551043, 2025). "The most extensively investigated include presenilin 1 (PSEN1), presenilin 2 (PSEN2), and amyloid precursor protein (APP) mutations, all of which contribute to elevated Aβ deposition and have been linked to familial Alzheimer’s disease." (PMID 41007636, 2025). "Amyloid precursor protein (APP) is a single-pass transmembrane protein abundantly expressed in the central nervous system and implicated in familial Alzheimer’s disease, a progressive neurodegenerative disorder that impairs memory." (PMID 39603510, 2024). "Most cases of familial Alzheimer’s disease are caused by heterozygous monogenic mutations of APP, among which the Swedish mutation (APPswe, K670N/M671L) is located at the cleavage site of β-secretase, resulting in stronger cleavage and excess Aβ production." (PMID 38972974, 2024). "Significantly, dominantly inherited mutations in both presenilins and APP currently represent the sole known causes of familial Alzheimer’s disease (FAD)." (PMID 38607048, 2024). "Organoids derived from familial AD (FAD): This model was established by generating iPSC-derived brain organoids from patients with familial Alzheimer’s disease (FAD) carrying APP duplications or mutations in the presenilin 1 (PSEN1) gene." (PMID 38727281, 2024). "More recently, Saito and colleagues generated a mouse model by knocking in mutations associated with familial Alzheimer’s disease into the APP gene." (PMID 39595581, 2024). "Palm11-PrRP31 treatment lowered astrocytosis, as it did previously in APP/PS1 mice overexpressing chimeric amyloid precursor protein with mutations found in familial Alzheimer’s disease and presenilin." (PMID 36678151, 2023). "Early-onset, familial Alzheimer’s disease (AD), with a prevalence of around 1%, is known to be associated with high-penetrance mutations in the genes coding for amyloid precursor protein (APP), presenilin 1 (PSEN1), and presenilin 2 (PSEN2)." (PMID 35736408, 2022). "Mutations in β-amyloid (Aβ) precursor protein (APP) cause familial Alzheimer’s disease (AD) probably by enhancing Aβ peptides production from APP." (PMID 36260691, 2022). "The most established pathogenic role of the GSC is in familial Alzheimer’s disease (fAD) through dysregulation of amyloid precursor protein (APP) cleavage and the generation of amyloid ß in neural tissues." (PMID 36118898, 2022). "We further report decreased TTL expression in sporadic and familial Alzheimer’s disease, and reduced microtubule dynamics in human neurons harbouring the familial APP-V717I mutation." (PMID 35148384, 2022). "Various studies have shown a link between the mutations of APP and AD; for example 10–15% cases of early-onset-familial Alzheimer’s disease (EOFAD) are reported to be caused by APP gene mutations." (PMID 36158539, 2022). "5X familial Alzheimer’s disease (5XFAD) model mice with mutated amyloid beta precursor protein (APP) and presenilin (PSEN1 and PSEN2) genes are widely used in AD studies, as they quickly simulate the main pathological features of amyloid protein." (PMID 34819847, 2021). "APP Swedish, which is adjacent to the β-secretase site in APP, is one of the well-known genetic mutations in familial Alzheimer's disease, resulting in increased total Aβ production." (PMID 33815510, 2021). "Previously, duplications of APP were reported to be causative variants for early onset familial Alzheimer disease." (PMID 32223758, 2020). "Because mutations in APP cause familial Alzheimer’s disease (fAD), most research focuses on this aspect of APP biology." (PMID 33290404, 2020).
familial Alzheimer disease (continued). "APP also undergoes extensive processing, and mutations in APP are associated with familial Alzheimer’s disease (AD)." (PMID 32764794, 2020). "Mutations and duplications of amyloid beta precursor protein (APP) gene have been implicated in familial Alzheimer’s disease, while brains of sporadic Alzheimer’s patients show increased mosaic APP copy number variation compared to healthy individuals." (PMID 31372185, 2019). "We have tested the functional significance of BACE1 processing of APP using App‐Swedish (Apps) knock‐in rats, which carry an App mutation that causes familial Alzheimer's disease (FAD) in humans." (PMID 31496118, 2019). "In this study, we induced the expression of human Swedish mutant APP associated with familial Alzheimer's disease." (PMID 30226901, 2018). "The mechanism by which familial Alzheimer’s disease (FAD) mutations within the transmembrane domain (TMD) of the Amyloid Precursor Protein (APP) affect ε-endoproteolysis is only poorly understood." (PMID 29966005, 2018). "Unlike sporadic Alzheimer’s disease, these experimental models express varying levels of APP, either in its wild-type form or as Mendelian variants associated with familial Alzheimer’s disease." (PMID 28852095, 2017). "The expression of the amyloid precursor protein (APP) with mutations found in familial Alzheimer’s disease also triggered similar autophagic-lysosomal pathologies." (PMID 28737703, 2017). "Mutations in APP and in genes that produce the presenilin enzymes that are part of the γ‐secretase complex that cleaves APP are correlated with cases of familial Alzheimer's disease (Tanzi, 2012; reviewed Selkoe & Hardy, 2016)." (PMID 27557896, 2016). "The amyloid precursor protein (APP), whose mutations cause familial Alzheimer’s disease, interacts with the synaptic release machinery, suggesting a role in neurotransmission." (PMID 26551565, 2015). "5xFAD mice overexpress (under control of Thy1 promoter) both mutant human APP with the Swedish (K670N, M671L), Florida (I716V), and London (V717I) familial Alzheimer's disease (FAD) mutations and human PSEN1 harboring two FAD mutations (M146L and L286V)." (PMID 25883808, 2015). "Lithium, a specific inhibitor of GSK-3α and GSK-3β, reduces Aβ production by interfering with APP cleavage at the γ-secretase step and is found to reduce Aβ production in the mice expressing pathogenic familial Alzheimer's disease." (PMID 24983010, 2014). "For example, mutations in APP linked to familial Alzheimer's disease increase the extracellular concentration of amyloid β protein (Aβ) in vivo." (PMID 24376773, 2013). "While mutations in APP lead to the development of Familial Alzheimer's Disease (FAD), sporadic AD has only one clear genetic modifier: the ε4 allele of the apolipoprotein E (ApoE) gene." (PMID 22363792, 2012). "Early-onset forms of familial Alzheimer's disease (FAD) have been linked to mutations in amyloid precursor protein (APP), presenilin-1 (PS-1), and presenilin-2 (PS-2)." (PMID 22888461, 2012). "Amyloid precursor protein (APP) mutations associated with familial Alzheimer's disease (AD) usually lead to increases in amyloid β-protein (Aβ) levels or aggregation." (PMID 22558227, 2012). "Mutations in APP lead to the development of Familial Alzheimer's Disease (FAD), however, the normal function of this protein has proven elusive." (PMID 20862215, 2010). "APPL is a homologue of mammalian Amyloid precursor protein (APP), which is one of the identified causative genes of familial Alzheimer's disease." (PMID 19209226, 2009). "The effect of preventing the caspase cleavage of APP on the Alzheimer's phenotype was evaluated in AD model transgenic mice that express APP with Swedish and Indiana mutations that are associated with familial Alzheimer's disease." (PMID 19558683, 2009). "Mutations leading to increased APP levels or alterations in APP cleavage cause familial Alzheimer's disease (AD)." (PMID 18575606, 2008).